DRD4 (dopamine receptor D4)
Diseases named in the same sentence as DRD4 in open-access papers (continued):
Sharing a sentence is not in itself a finding about the gene and the disease.
impulse control disorder (2 papers, 2012 to 2024). A category of behaviors that can be loosely defined as the failure to resist an impulsive act or behavior that may be harmful to self or others. "There is substantial genetic influence in impulse-control disorders: for instance, the dopamine D4 receptor (DRD4) is the prototypic polymorphic gene, subserving a background for novelty- and risk- seeking, addiction as well as both ADHD and OCD." (PMID 23192105, 2012).
neuroblastoma (2 papers, 2006 to 2009). Neuroblastoma (NB) is the most common solid, extracranial childhood tumor. "In neuroblastoma cells, the induction of DRD4 was much more pronounced (about eightfold compared to 48-hr untreated control levels) than that of DRD3." (PMID 19653907, 2009). "In addition to these cells, another neuroblastoma cell line (SK-N-F1) was also shown to produce high level of DRD4 mRNA in our study." (PMID 16723017, 2006). "This theory was based on previously reported discrepancies in the size of the DRD4 mRNA which was originally reported as 5.3 kb in the SK-N-MC human neuroblastoma cell line and in the striatum, medulla, frontal cortex and limbic area of the rat and monkey brain." (PMID 16723017, 2006). "The human Y79 and IMR32 neuroblastoma cell lines reportedly express DRD4 mRNA." (PMID 16723017, 2006). "In conclusion, there seems to be an inverse correlation between DRD3/DRD4 and DRRF levels in the context of SK-NF-I neuroblastoma cells." (PMID 19653907, 2009).
somatotropinomas (2 papers, 2018 to 2019). "In conclusion, the systematic evaluation of DRD and SSTR expression in somatotropinomas has revealed an association between the response to SSAs treatment and DRD4, DRD5, SSTR1 and SSTR2 expression." (PMID 29266696, 2018).
tic disorder (2 papers, 2014 to 2018). Disorders characterized by recurrent TICS that may interfere with speech and other activities. "Their results revealed an association between the longer alleles of DRD4 exon III 48 bp VNTR polymorphism and tic disorder accompanied with ADHD, thus suggesting a possible genetic risk factor of tic disorder with ADHD in Chinese." (PMID 30542299, 2018).
withdrawal syndrome (2 papers, 2020 to 2023). "In addition, animal studies showed the beneficial impact of some DRD4 antagonists to attenuate or reverse the rewarding effects of cocaine and methamphetamine, morphine-induced withdrawal syndrome, and nicotine reinstatement." (PMID 36854793, 2023).
Abdominal obesity (1 paper, 2023). Excessive fat around the stomach and abdomen. "Our finding showing that carriers of DRD4-L alleles had a higher risk of abdominal obesity is in line with the previous relationship described between DRD4-VNTR and weight gain after antipsychotic treatment." (PMID 37631349, 2023).
acute myeloid leukemia (1 paper, 2023). Acute myeloid leukemia (AML) is a group of neoplasms arising from precursor cells committed to the myeloid cell-line differentiation. "For instance, DRD3 is only expressed in glioblastoma and is expressed at lower levels than in a healthy brain, while DRD4 is overexpressed only in acute myeloid leukemia (AML)." (PMID 37509555, 2023).
aging (1 paper, 2021). A developmental process that is a deterioration and loss of function over time. "First, we explored the associations between cognitive aging and the dopamine receptor-related loci, including the DRD1, NCAM1-TTC12-ANKK1-DRD2, DRD3-LOC107986115-ZNF80-TIGIT-MIR568-ZBTB20, DRD4, and DRD5-SLC2A9 loci." (PMID 34285142, 2021).
alcohol-related disorders (1 paper, 2014). Disorders related to or resulting from abuse or mis-use of alcohol. "Korean children of alcoholics have been shown to be significantly more likely to carry the 4-repeat allele and the 4/4 genotype of DRD4 than are control subjects, indicating the possibility of genetic vulnerability toward alcohol-related disorders existing alongside a higher morbidity of ADHD." (PMID 24978879, 2014).
allergic reactions (1 paper, 2023). "It has been shown that DA signals via DRD4 to promote Th2 responses, with implications for allergic reactions." (PMID 37376663, 2023).
astrocytoma (1 paper, 2009). "In contrast, the DRD3 was much more inducible than DRD4 in astrocytoma cells, and its mRNA levels were highly elevated already after 24 hr hypoxia." (PMID 19653907, 2009).
cocaine addiction (1 paper, 2012). "Concerning the known dopamine receptors, it has been reported that DRD1 and DRD2 are the most involved in cocaine addiction, whereas DRD3 and DRD4 are less relevant in the addiction process." (PMID 23285158, 2012).
colorectal adenoma (1 paper, 2025). An adenoma that arises from the colon or rectum. "To validate these online data, we assessed DRD4 expression in normal colorectal tissues, colorectal adenomas, CRC primary tumors, and liver metastases by immunohistochemistry (IHC) assay." (PMID 39679842, 2025).
COVID-19 (1 paper, 2025). A disease caused by infection with severe acute respiratory syndrome coronavirus 2. "The indirect paths between rumination and DRD1/DRD4 expression in PBMCs were significant only in cohort II, suggesting that cognitive processes, such as repetitive negative thinking, may relate to dopaminergic pathways in recently discharged COVID-19 patients." (PMID 41574058, 2025). "While previous studies suggest that DA can supress NLRP3, leucine-rich repeat (LRR), and pyrin domain-containing protein 3 (NLRP3) inflammasome activation via DRD1 pathways, our findings indicate that DRD4 may not mediate this mechanism in the context of post-COVID-19 recovery." (PMID 41574058, 2025).
developmental delays (1 paper, 2016). "The 11p15.5 microdeletion contains amongst others the DRD4 gene responsible for regulating many neurological functions related to psychiatric disorders, developmental delays, as well as to neuroleptic response." (PMID 27651829, 2016).
diabetic retinopathy (1 paper, 2017). "Since diabetic retinopathy affects dopamine content and rhythmicity of Drd4 expression (this study), the disturbed circadian regulation of Gnaz may reflect dysfunction of the retinal dopaminergic system under diabetic conditions." (PMID 29088301, 2017).
drug dependence (1 paper, 2020). "Disruption of this pathway, in which DRD4 seems to play a critical role, can lead to psychiatric disorders, including drug dependence, food addiction and ED." (PMID 32751662, 2020).
Dyskinesia (1 paper, 2024). A movement disorder which consists of effects including diminished voluntary movements and the presence of involuntary movements. "The significant variables associated with ICD development were sex (OR 2.61; CI 1.26–5.39, p = 0.009), age at PD onset (OR 0.96; CI 0.93–0.99, p = 0.013), DRD4 7+ polymorphism (OR 2.23; CI 1.13–4.42, p = 0.021), and presence of dyskinesias (OR 2.31; CI 1.18–4.53, p = 0.015)." (PMID 38952083, 2024). "We included in the multivariable logistic regression equation sex, age of PD onset, DRD4 7+, and dyskinesias as covariates, and the presence of ICD versus non‐ICBs and ICBs as the dependent variable." (PMID 38952083, 2024).
epilepsy (1 paper, 2025). A brain disorder characterized by episodes of abnormally increased neuronal discharge resulting in transient episodes of sensory or motor neurological dysfunction, or psychic dysfunction. "Meanwhile, the SMR analysis indicated a strong association between the expression of DRD4 and ADRA1D and epilepsy or its subtypes." (PMID 40170563, 2025). "SMR showed that DRD4 and ADRA1D were strongly associated with epilepsy or its subtypes however, neither gene passed the HEIDI test." (PMID 40170563, 2025).
Huntington disease (1 paper, 2024). Huntington disease (HD) is a rare neurodegenerative disorder of the central nervous system characterized by unwanted choreatic movements, behavioral and psychiatric disturbances and dementia. "The results showed that AKT1 mainly involves 12 pathways, with the most significant being ubiquitin-mediated proteolysis; DRD4 mainly involves 7 pathways, with the most significant being AA metabolism; KMO mainly involves 4 pathways, with the most significant being Huntington disease." (PMID 39312335, 2024).
Hypertension (1 paper, 2021). The presence of chronic increased pressure in the systemic arterial system. "The hypertension in Drd4−/− in mice is related in part to an increased AT1R activity; the expression of AT1R is increased in the organs studied, brain and kidney." (PMID 33535566, 2021).
infarction (1 paper, 2020). A localised pathological necrosis of tissue resulting from obstruction of the blood supply usually by a thrombus, an embolus, or vascular torsion. "DRD4 activation improved left ventricular systolic function and decreased infarction size during I/R injury." (PMID 33584304, 2020).
insomnia (1 paper, 2025). A sleep disorder characterized by difficulty in falling asleep and/or remaining asleep. "In silico studies demonstrated that protopine, rutin, eschscholtzidine, boldine, and (S)‐scoulerine exhibited notable inhibitory effects on insomnia‐related DRD5, DRD4, and SERT proteins." (PMID 40909255, 2025). "In silico studies demonstrated that protopine, rutin, eschscholtzidine, boldine, and scoulerine exhibited notable inhibitory effects on insomnia‐related proteins, specifically DRD5, DRD4, and SERT." (PMID 40909255, 2025).
Insulin resistance (1 paper, 2023). Increased resistance towards insulin, that is, diminished effectiveness of insulin in reducing blood glucose levels. "Nevertheless, we found moderate positive correlations between DRD1/DRD4 and GLP1R, especially in patients with insulin resistance, suggesting that GLP1R expression is associated with the decreased expression of dopamine receptors in patients with insulin resistance." (PMID 36768789, 2023). "Such moderate positive correlations are maintained and increased only in patients with insulin resistance in relation to DRD1 (r = 0.386, p = 0.0008) and DRD4 (r = 0.419, p = 0.0003), being absent in insulin-sensitive patients." (PMID 36768789, 2023).
lupus (1 paper, 2018). "In addition to shaping T cell differentiation and function, dopamine could trigger T cell quiescence through DRD4, and that suggests a new way to treat lupus based on the higher expression of DRD4 in systemic lupus erythematosus patients." (PMID 30386344, 2018).
medulloblastoma (1 paper, 2014). A malignant, invasive embryonal neoplasm arising from the cerebellum. "Interestingly, a recent report describing epigenetic repression of the dopamine receptor family member, DRD4, in primary medulloblastoma adds further support for a significant role for deregulated dopamine signalling in medulloblastoma pathogenesis." (PMID 25412507, 2014).
melanoma (1 paper, 2022). A malignant, usually aggressive tumor composed of atypical, neoplastic melanocytes. "Significant up-regulation of DRD4 expression in melanomas after hu14.18-IL2 treatment was found (Padj < 1 × 10−8)." (PMID 35053262, 2022). "Following mined data, all dopamine receptors were detected in melanomas; among them DRD1 in 33.8%, DRD2 in 11.3%, DRD3 in 4.5%, DRD4 in 62.4%, and DRD5 24.1% of samples." (PMID 35053262, 2022).
myocardial infarction (1 paper, 2020). Gross necrosis of the myocardium, as a result of interruption of the blood supply to the area, as in coronary thrombosis. "Compared with the I/R group, DRD4 activation by PD168077 markedly decreased myocardial infarction size, profoundly improved cardiac function, evidenced by the lower LVEDP, higher +dp/dt (%) and LVDP." (PMID 33584304, 2020).
panic disorder (1 paper, 2023). An anxiety disorder characterized by multiple unexpected panic attacks with persistent concern of recurring attacks. "However, Drd4 is a candidate gene for obsessive–compulsive disorder and panic disorder." (PMID 37008785, 2023).
prediabetes (1 paper, 2025). "The DA D4 receptor (DRD4), another D2-like receptor, was also upregulated in adipose tissue of patients with prediabetes." (PMID 39906261, 2025).
sialorrhea (1 paper, 2023). "Indeed, the 120 bp duplication in the DRD4 gene is significantly associated with clozapine-induced sialorrhea, suggesting that this duplication may increase the risk of sialorrhea in TRS patients treated with clozapine." (PMID 36983018, 2023).
substance-related disorder (1 paper, 2020). A category of psychiatric disorders which include disorders related to the taking of a drug of abuse (including alcohol, prescribed medications and recreational drugs). "The DRD4 4/4 polymorphism was shown to be a risk genotype for substance-related disorders." (PMID 33361057, 2020).
Visual hallucination (1 paper, 2022). Visual perception in the absence of a visual stimulus. "In addition, visual hallucinations occurred significantly earlier in PD patients carrying DRD1 –48 GG and 62TT alleles in this study, whereas DRD4 CG alleles of 747,302 were associated with later onset of hallucinations, compared to DRD4 CC alleles." (PMID 35741861, 2022).
psychiatric disorder (26 papers, 2005 to 2024). A disorder characterized by behavioral and/or psychological abnormalities, often accompanied by physical symptoms. "This study has uncovered significant associations between rs6265 in BDNF, rs1800955 in DRD4, and psychiatric disorders in a general cohort of patients with mental illnesses compared to the controls." (PMID 38397229, 2024). "The dopamine receptor D4 (DRD4) gene 48 bp variable number of tandem repeats (VNTR) polymorphism at the third exon has been previously reported to be linked with mental illness or behavioral traits in different patient settings." (PMID 33784353, 2021). "DRD4 gene encodes a subtype of DA receptor that regulates many neurological processes connecting with psychiatric disorders." (PMID 24586542, 2014). "Further functional studies as well as studies evaluating DRD4 variability in other psychiatric disorders are needed to better understand the role of these mutations in disease etiology." (PMID 24391992, 2013). "DRD4 has been implicated in several psychiatric disease phenotypes and our results shed light upon the possible mode of action of SNP associations in this region." (PMID 22691691, 2012). "Dopamine receptor D4(DRD4) polymorphisms have been associated with a number of psychiatric disorders, but little is known about the mechanism of these associations." (PMID 22691691, 2012). "Polymorphisms in the DRD4 gene have received particular attention in the past decade because of their possible role in mental disorders, substance abuse and the normal variations of human personality." (PMID 15985158, 2005). "Given that the dopaminergic and serotonergic pathways are involved in the etiology of psychiatric disease, this study evaluated the genetic association of dopamine D4 receptor (DRD4) and serotonin transporter (SLC6A4) genes with psychiatric symptom susceptibility among HD patients." (PMID 33784353, 2021). "Promoter polymorphisms of the DRD4 gene, including the 120 base pair (bp) duplication and several SNPs (-521 C/T, -616 G/C SNP), have been extensively studied as possible risk factors of psychological traits as well as behavioural and psychiatric disorders." (PMID 16723017, 2006). "In recent years, several selective ligands have been developed and employed to examine DRD4 as a potential target in treating psychiatric disorders." (PMID 36854793, 2023). "The human dopamine D4 receptor (DRD4) gene has been studied extensively as a candidate gene for certain psychological traits and several behavioural and psychiatric disorders." (PMID 16723017, 2006). "The DRD4 plays an important role in cognitive functions and it is a target of numerous antipsychotic drugs widely used in psychiatric disorders." (PMID 16723017, 2006). "The human dopamine D4 receptor (DRD4) is a candidate gene of great interest in molecular studies of human personality and psychiatric disorders." (PMID 15985158, 2005). "The two DRD4 polymorphisms analyzed in our study were repeatedly shown to be associated with a range of psychiatric disorders, but there was no pre-existing information on possible links between these gene variants and cancer." (PMID 33868590, 2021). "DRD4 exon III (VNTR) polymorphism was reported as a candidate genetic variant associated with substance use disorder (SUD) susceptibility in different populations as well as a number of approach-oriented behavioral phenotypes and psychiatric disorders." (PMID 33171585, 2020). "Additionally, there is evidence of interactions between SOB and specific genetic polymorphisms, such as the dopamine receptor D4 (DRD4) 48 bp VNTR polymorphism, on psychiatric disorders and BMI." (PMID 18030347, 2007). "Thus, the role of DRD4 has been revealed in a number of pathological processes in the brain, contributing for the receptors to become a promising target in pharmacotherapy of many psychiatric disorders." (PMID 36854793, 2023).
psychiatric disorder (continued). "To demonstrate the utility of BECon, we assessed key candidate genes often investigated for changes in DNAm in relation to psychiatric disorders (BDNF, COMT, OXTR and DRD4)." (PMID 28763057, 2017). "Using a meta-analytic approach, the authors found that the 7R allele of DRD4 was specifically implicated in ADHD and no with any other psychiatric diseases, validating our data both as regards the 7R allele as a major risk susceptibility factor for ADHD and as regards its specificity for ADHD." (PMID 32075956, 2020). "Lastly, more recent neuroimaging studies showed that the presence of some DRD2 and DRD4 might, respectively, modulate the gyrification and the functional activity of cortical areas involved in cognitive processes that are impaired in ADHD and other psychiatric disorders." (PMID 34658761, 2021).